MTA3 (metastasis associated 1 family member 3)
Diseases named in the same sentence as MTA3 in open-access papers (continued):
Sharing a sentence is not in itself a finding about the gene and the disease.
endometrioid adenocarcinoma (3 papers, 2013 to 2017). An adenocarcinoma characterized by the presence of malignant glandular epithelial cells resembling endometrial cells. "It would be extremely intriguing and important to examine whether MTA3 expression could serve as a biomarker to differentiate endometrioid from non-endometrioid carcinomas." (PMID 28279208, 2017).
fibrosis (3 papers, 2022 to 2025). the formation of excess fibrous connective tissue in an organ or tissue in a reparative or reactive process. "Sirius red staining revealed that mice in the myocardial infarction model group developed significant fibrosis, and overexpression of MTA3 significantly alleviated cardiac fibrosis." (PMID 40615041, 2025). "For example, genistein improves cardiac dysfunction induced by mechanical overload and attenuates cardiac fibrosis by regulating the MTA3/TAK1/MKK4/JNK signaling cascade, highlighting its potential as a novel agent for preventing and treating fibrosis-related cardiovascular diseases." (PMID 41584603, 2025). "In conclusion, MTA3 regulates cardiac fibrosis through the p38 MAPK-E2F1 axis." (PMID 40615041, 2025).
melanoma (3 papers, 2012 to 2023). A malignant, usually aggressive tumor composed of atypical, neoplastic melanocytes. "Strikingly, among these, neurotrophin signaling, MTA-3 downregulation, cell cycle deregulation, and glycolysis/gluconeogenesis have been implicated in the development and progression of melanoma and other cancers." (PMID 22906024, 2012). "Next, we performed ChIP quantitative PCR assays of melanoma cell lines to validate c-Myc as the target gene of MTA3, and MTA3 was found to directly bind at the region of the c-Myc promoter." (PMID 36050478, 2022). "SPHK1- or MTA3-OE cells showed significantly increased melanoma growth compared with B16F10CTL cells." (PMID 36050478, 2022). "To assess the prognostic features of MTA3 in melanoma patients, we extracted time-to-event data and conducted survival analyses." (PMID 36050478, 2022). "In this study, we observed the expression of MTA3 in melanoma cells and proved that MTA3 boosted melanoma progression in vivo." (PMID 36050478, 2022). "SPHK1 and MTA3 hold the potential to function as novel biomarkers to predict melanoma patient outcomes upon anti-PD-1 mAb blockade therapy." (PMID 36050478, 2022). "Significantly, we identified SPHK1 and MTA3 as biological markers for predicting the efficacy of anti-PD-1 mAb therapy in melanoma patients." (PMID 36050478, 2022). "To this end, we first generated poorly immunogenic B16F10 mouse melanoma cells stably overexpressing SPHK1 or MTA3." (PMID 36050478, 2022). "Our findings revealed a novel role for SPHK1 in tumor evasion mediated by regulating the MTA3-PD-L1 axis, identified SPHK1 and MTA3 as predictors for assessing the efficacy of PD-1 mAb treatment, and provided a therapeutic possibility for the treatment of melanoma patients." (PMID 36050478, 2022). "Furthermore, we delineated the expression of SPHK1, MTA3, c-Myc, and PD-L1 and tumor-infiltrating immune cell profiles in melanoma biopsies from a total of nineteen patients regularly receiving PD-1 blockade therapies (toripalimab)." (PMID 36050478, 2022). "Multiplex IHC staining showed that overexpression of SPHK1 or MTA3 significantly boosted PD-L1+ cells but decreased the density of CD8+ T cells in the tumor region, indicating that SPHK1-MTA3-PD-L1 axis-mediated immune escape contributes to melanoma progression." (PMID 36050478, 2022). "As PD-1 on CD8+ T-cell subsets is a novel identified marker in predicting the response to anti-PD-1 immunotherapies, these data suggest that SPHK1 and MTA3 may serve as potential biomarkers for the prognosis of melanoma and the efficacy of PD-1 mAb blockade therapies." (PMID 36050478, 2022). "Correlation analyses suggested a significant difference in PD-L1 membrane expression between the melanoma population with high or low cytoplasmic expression of SPHK1 (p = 9.85 × 10−4), or with high or low nuclear expression of MTA3 (p = 5.48 × 10−3)." (PMID 36050478, 2022). "Importantly, the results showed that compared with IgG2a treatments, PD-1 blockade therapies significantly reversed SPHK1- or MTA3-associated immune dysfunctions and enhanced the immune response against tumor cells, as reflected by the frequencies of CD8+ and GZMB+CD8+ T lymphocytes in melanoma." (PMID 36050478, 2022). "Our results showed that the knockdown of MTA3 resulted in significantly decreased levels of IFN-γ-induced PD-L1 and c-Myc in melanoma cell lines in vitro." (PMID 36050478, 2022). "The goal of this study was to assess the role of SPHK1 in antitumor immunity, reveal a novel molecular mechanism regarding the regulation of PD-L1 via MTA3, and further investigate the clinical significance of the SPHK1-MTA3 axis in immunotherapy in melanoma." (PMID 36050478, 2022). "To test this hypothesis, we established melanoma cell lines stably overexpressing Flag-SPHK1 driven by lentiviral vectors and subsequently knocked down MTA3." (PMID 36050478, 2022).
melanoma (continued). "In addition, MTA3 was first found to be a potential target of SPHK1 and to participate in the transcriptional regulation of PD-L1 in malignant melanoma." (PMID 36050478, 2022). "Importantly, the role of MTA3 in stabilizing immunosuppression in the TME provides new insights for future investigation of and clinical therapeutics in melanoma." (PMID 36050478, 2022). "Importantly, melanoma cells with high SPHK1 and MTA3 expression were found to be highly sensitive to anti-PD-1 mAb-mediated tumor cytotoxic effects in vivo." (PMID 36050478, 2022). "Consistent with our observations, the suppression of SPHK1 in melanoma cell lines in vitro, either by treatment with PF543 or with an SPHK1-targeting short interfering RNA (siRNA), produced reductions in the MTA3 and c-Myc expression levels." (PMID 36050478, 2022).
B-cell chronic lymphocytic leukemia (2 papers, 2013 to 2025). "Patients with high lipoprotein lipase mRNA expression in B-cell chronic lymphocytic leukemia (B-CLL) demonstrate significantly higher MTA3 signaling activity, which is associated with adverse cytogenetic profiles, shorter time to first treatment, and reduced overall survival." (PMID 41584603, 2025). "MTA3 was reported to participate in B lymphocyte development, in plasmacytoma cell lines, the overexpression of BCL6 (B-cell CLL/lymphoma 6) and MTA3 downregulated plasma cell differentiation genes." (PMID 24107548, 2013).
esophageal squamous cell carcinoma (2 papers, 2021 to 2023). Esophageal squamous cell carcinoma (ESCC) is a type of esophageal carcinoma (EC) that can affect any part of the esophagus, but is usually located in the upper or middle third. "The MTA3/SOX2‐OT/SOX2 axis has been involved as a prognostic factor for poor clinical outcomes in esophageal squamous cell carcinoma patients." (PMID 33433063, 2021). "This would propose the MTA3/SOX2‐OT/SOX2 axis as a potential cancer stratification molecular‐marker, and therapeutic targets in human esophageal squamous cell carcinomas." (PMID 33433063, 2021). "Moreover, MTA3 downregulates SOX2OT, and the MTA3/SOX2-OT/SOX2 axis has been reported as a potential cancer stratification marker in human esophageal squamous cell carcinomas." (PMID 37519889, 2023).
myocardial infarction (2 papers, 2025). Gross necrosis of the myocardium, as a result of interruption of the blood supply to the area, as in coronary thrombosis. "Future clinical trials should evaluate the safety and efficacy of MTA3 modulators in fibrosis-associated conditions, including myocardial infarction and heart failure." (PMID 41584603, 2025). "To further clarify the correlation between MTA3 and cardiac fibrosis, we overexpressed MTA3 in cardiac fibroblasts specifically by adeno-associated virus in mice with myocardial infarction." (PMID 40615041, 2025). "Overexpression of MTA3 could significantly reverse the cardiac function caused by myocardial infarction and inhibit the expression of myofibroblasts markers." (PMID 40615041, 2025). "To study the role of MTA3 in cardiac fibrosis, we first analyzed cardiac MTA3 expression in mice subjected to myocardial infarction (MI) through ligation of the left anterior descending coronary artery." (PMID 40615041, 2025). "To further investigate the specific mechanism by which MTA3 regulates myocardial fibrosis, we first compared the expression differences of MTA3 in primary cardiomyocytes and fibroblasts from myocardial infarction (MI) mice and sham controls." (PMID 40615041, 2025). "Though the p38 MAPK protein level remained unchanged, the expression of phosphorylated p38 MAPK protein was significantly increased after MTA3 was knocked down under normal and myocardial infarction conditions." (PMID 40615041, 2025). "Our study used a well-established murine myocardial infarction model of myocardial infarction and primary cardiac fibroblasts from neonatal mice to explore how MTA3 induces the transformation of fibroblast-to-myofibroblast transition (FMT) by regulating downstream E2F1 during cardiac fibrosis." (PMID 40615041, 2025). "We found that AAV9-mediated MTA3 overexpression could inhibit cardiac fibrosis and improve cardiac function after myocardial infarction." (PMID 40615041, 2025). "The cardiac function of mice was evaluated by echocardiography, and it was found that the cardiac function of mice with a myocardial infarction model after overexpression of MTA3 was significantly restored, and the EF% and FS% values were significantly increased." (PMID 40615041, 2025). "In contrast, there was no significant change in the expression level of MTA3 protein in cardiomyocytes after myocardial infarction." (PMID 40615041, 2025).
plasmacytoma (2 papers, 2013). Plasmacytoma is a localized mass of neoplastic monoclonal plasma cells that represents approximately 5% of all plasma cell neoplasms. "MTA3 was reported to participate in B lymphocyte development, in plasmacytoma cell lines, the overexpression of BCL6 and MTA3 downregulated plasma cell differentiation genes." (PMID 23840517, 2013).
preeclampsia (2 papers, 2024 to 2025). Preeclampsia is a hypertensive disorder of pregnancy that is characterized by new-onset hypertension with proteinuria presenting after 20 weeks of gestation, and depending on mild or severe forms may initially present with severe headache, visual disturbances, and hyperreflexia. "Previous research delineated a significant downregulation of Metastasis-associated protein 3 (MTA3) in the placenta affected by preeclampsia, in contrast to the upregulation of both CGB5 and Snail." (PMID 39544937, 2024). "Aberrant MTA3 expression is associated with the pathogenesis of preeclampsia." (PMID 41584603, 2025). "Accumulating evidence indicates that MTA3 expression is significantly downregulated in placental tissues from patients with preeclampsia." (PMID 41584603, 2025).
brain arteriovenous malformations (1 paper, 2023). "Finally, SCENIC analysis identified TWIST2, MTA3, and SMAP2 as possible key EndMT EC differentiation-regulating TFs, among which TWIST2 has been confirmed as the key TF in EndMT ECs in brain arteriovenous malformations." (PMID 37853464, 2023).
brain glioma (1 paper, 2017). A malignant glioma that involves the brain. "The expression level of MTA3 was found to be down-regulated in human brain glioma and closely correlated to clinicopathologic characteristics and outcome of patients." (PMID 28418887, 2017).
carcinoma in situ (1 paper, 2019). "Next, we studied the expression of MTA3/SOX2 in normal tongue tissue samples, hyperplasia, carcinoma in situ, early invasive carcinoma and invasive carcinoma by immunohistochemistry." (PMID 31552166, 2019).
carcinoma of the esophagus (1 paper, 2017). "Emerging evidence suggested that MTA3 aberrantly expressed in multiple cancers, including carcinoma of the esophagus, breast, lung, uterus and nasopharynx." (PMID 28968973, 2017).
chronic myelogenous leukemia (1 paper, 2022). "We found that MTA3 peaks localize close to the c-Myc promoter region in the K562 chronic myelogenous leukemia cell line, implying that it might regulate c-Myc transcriptionally." (PMID 36050478, 2022).
dermatomyositis (1 paper, 2016). Dermatomyositis (DM) is a type of idiopathic inflammatory myopathy characterized by evocative skin lesions and symmetrical proximal muscle weakness. "The NuRD multiprotein complex includes the dermatomyositis-specific Mi2 autoantigen (Mi2-β), RB-associated proteins 46 and 48 (RbAp46 and RbAp48), MBD2 and MBD3, and metastasis-associated proteins 2 and 3 (MTA2 and MTA3)." (PMID 26810492, 2016).
diabetes (1 paper, 2024). "Other diabetes-related genes, such as FGFR3, MTA3, PAK4, and KIF22, had similar results." (PMID 39000600, 2024).
esophageal adenocarcinoma (1 paper, 2013). A malignant tumor with glandular differentiation arising predominantly from Barrett mucosa in the lower third of the esophagus. "Higher MTA3 levels were noted in normal esophagus relative to esophageal adenocarcinoma (P<0.001), and in normal gastric mucosa than in mixed-type gastric cancer or diffuse-type gastric cancer (P = 0.008 and P = 0.025)." (PMID 23671646, 2013). "In support of the role of MTA3 in metastasis, our analysis of MTA3 transcript in gastric and esophageal adenocarcinoma cell lines on CCLE identified a strongly inverse correlated tendency between MTA3 expression and the metastatic potential of the tumor cells." (PMID 23671646, 2013).
head and neck cancer (1 paper, 2019). A primary or metastatic malignant neoplasm affecting the head and neck. "However, the role of MTA3 in tongue squamous cell cancer (TSCC) remains unclear although it is the most prevalent head and neck cancer and often with poor prognosis." (PMID 31552166, 2019).
Hepatic fibrosis (1 paper, 2024). The presence of excessive fibrous connective tissue in the liver. "Furthermore, our results suggest that the transcription factor Mta3 in the MoMFs subset may be a key factor in the ability of JQF to alleviate hepatic fibrosis in NAFLD." (PMID 39840059, 2024).
leukemia (1 paper, 2023). A malignant (clonal) hematologic disorder, involving hematopoietic stem cells and characterized by the presence of primitive or atypical myeloid or lymphoid cells in the bone marrow and the blood. "In the leukemia cell lines tested, MTA3 is not expressed and MTA2 is a mild dependency." (PMID 36707513, 2023).
metastasis (1 paper, 2025). The spread or migration of cancer cells from one part of the body (where they first appeared) to another. "The MTA3-negative/Snail-positive/E-cadherin-negative phenotype was significantly associated with lymph node metastasis, advanced disease stage, and poorly differentiated tumors." (PMID 41584603, 2025).
myeloma (1 paper, 2013). "Interestingly, in a myeloma cell line model co-expression of BCL6 and MTA3 can drive a phenotypic reversion with B-cell antigen expression." (PMID 24385976, 2013).
Myocardial fibrosis (1 paper, 2025). "Studies have shown that during the process of TGFβ1-induced myocardial fibrosis, the expression of MTA3 protein is significantly down-regulated." (PMID 40615041, 2025). "Therefore, in-depth research on the regulatory effect and mechanism of MTA3 on myocardial fibrosis will provide more effective and accurate approaches for related research on cardiovascular system diseases." (PMID 40615041, 2025). "In this study, we found for the first time that MTA3 inhibits myocardial fibrosis by regulating the transformation of myocardial fibroblasts into myofibroblasts at the animal and cellular levels and revealed the detailed mechanism of the p38 MAPK-E2F1 signaling pathway." (PMID 40615041, 2025).
Sepsis (1 paper, 2025). Sepsis is defined as life-threatening organ dysfunction caused by a dysregulated host response to infection. "The precise role and underlying mechanisms of MTA3 in sepsis remain unclear." (PMID 41584603, 2025). "Recent bioinformatics analyses indicate that MTA3 may be involved in the pathogenesis of sepsis through PPI networks, particularly those involving genes such as MAP1LC3A." (PMID 41584603, 2025).
tongue cancer (1 paper, 2019). A malignant neoplasm affecting the tongue. "Further studies will better the understanding about the mechanisms in MTA3-regulated SOX2 expression in tongue cancer." (PMID 31552166, 2019).
uterine carcinoma (1 paper, 2013). A carcinoma involving a uterus. "Disregulation of MTA3 has been correlated with poor differentiation in endometrial cancer and poor prognosis in uterine carcinoma." (PMID 23671646, 2013). "Similarly, another recent study demonstrated that MTA3 was an independent prognostic indicator in uterine carcinoma." (PMID 23671646, 2013).